IGF1R (insulin like growth factor 1 receptor)
Diseases named in the same sentence as IGF1R in open-access papers (continued):
Sharing a sentence is not in itself a finding about the gene and the disease.
tumor (continued). "IGF1 and GAS6 act as paracrine-reciprocal signals for activating the receptor tyrosine kinases IGF1R and AXL (“anexelenko”, which means “uncontrolled” in Greek), respectively, in tumor cells." (PMID 35159011, 2022). "The uptake in tumors with high IGF-1R expression (MCF-7/HER2-18) was 2.5 ± 0.4% ID/g, and the tumor-to-blood ratio was 5.8 at 4 h after injection." (PMID 35890370, 2022). "To try to understand the mechanisms, we detected the expression of phospho-EGFR, -HER2, -IGF-1R, -AKT, and -ERK as well as their total protein levels in the xenograft tumor tissues by western blot analysis." (PMID 36142299, 2022). "IGF1R and AXL activate Akt signaling and increase mitochondrial performance, proliferation, and resistance to apoptosis in tumor cells." (PMID 35159011, 2022). "Cixutumumab and ramucirumab act against insulin-like growth factor-1 receptor (IGF-1R)/vascular endothelial growth factor receptor (VEGFR) and can prevent tumor growth." (PMID 35411277, 2022). "Second, the survival analysis showed that 7 genes had significant (p < 0.05) Kaplan–Meier curves, including 5 genes (MS4A1, N4BP2L1, IGF1R, TCF7L2 and COL11A1) based on the normal expression, and 2 genes (TCF7L1 and PTPRM) based on the tumor expression." (PMID 35406404, 2022). "Most of these tumor-related alterations belong to the kinases from the closest animal counterpart RTKs, such as RON, FGFR1-4, IGF-1R, ALK, c-Ret, c-Met, and HER-2." (PMID 35095975, 2021). "In animals bearing A549 xenografts, we demonstrated that the combination of two different IGF-1R inhibitors (linsitinib and GSK1838705A) with GCs had a significant effect on tumour size in comparison to the GC-monotherapy arm." (PMID 34272384, 2021). "Here, we found that reducing IGF2 expression levels or blocking IGF1R, using AEW541, combined with either isiPI3K, BYL719 or GDC0032, enhanced tumor growth arrest." (PMID 34067117, 2021). "Therefore, this seminal paper indicates that paracrine IGF/IGF1R signaling contributes to metabolic reprogramming (induction of lactate and glutamine consumption), a well-known mechanism in the immune-suppressive tumor microenvironment, due to M2 polarization and Treg selection." (PMID 34065119, 2021). "We then used Estrogen Receptor (ER)-positive BC cells, CRISPR-mediated IGF-1R KO BC cells, and isogenic S100A7-transduced BC cells to investigate the role of IGF-1/IGF-1R in the regulation of S100A7 expression and tumor angiogenesis." (PMID 33557316, 2021). "The detection rate of IGF1R rearrangements by FISH, however, was lower in our set of tumours (9.2%, n = 119)." (PMID 33295144, 2021). "Although the role of MSCs in the tumor microenvironment is still unclear, it has been shown that MSC secretions can downregulate IGF/IGF-1R signaling and inhibit HCC cell proliferation." (PMID 33669204, 2021). "Another anti-IGF-1R monoclonal antibody, R1507 (RG1507), has shown encouraging results, inducing tumor shrinkage in 5% of OST patients, but its development has been terminated by the producer company." (PMID 33917001, 2021). "In ovarian cancer, the activation of the IGF1R/STAT3 axis promotes cell migration, invasion and in vitro spheroid formation and induces in vivo tumor growth." (PMID 33673232, 2021). "According to published research, miR-491-3p directly targeted insulin-like growth factor 1 receptor (IGF1R) and MKK7, a mitogen-activated protein kinase, to suppress tumor metastasis." (PMID 33098307, 2021). "For example, the insulin and insulin-like growth factor-1 receptor (IGF-1R) signaling pathways are known to enhance the development and progression of PDAC by promoting tumor growth and metastasis and by driving therapy resistance." (PMID 34440625, 2021). "Various degradative enzymes, either in the tumor cells or in host cells, are induced to do so by tumor-derived factors related to retinoid signaling such as RAI2 or through retinoid-independent metastasis modulators such as WRN, IGF1-R, TGF-β1 and E-cadherin." (PMID 33477997, 2021).
tumor (continued). "The IGF-1R siRNA/DOX co-delivery system loaded chitosan nanoparticles play an effective role in reducing mmp9, STAT3, and VEGF in tumor cells." (PMID 33768092, 2021). "It appears that accumulation of DNA damage leads to abrogation of the physical interplay between IGF1R and PCNA as the tumor progresses, with ensuing reduction in genomic stability." (PMID 33918477, 2021). "IGF-1 interactions with its cognate receptor IGF-1R on the surface of tumor cells and phosphatidylinositol 3-kinase (PI3K) signaling pathway activation resulted in tumor resistance and proliferation." (PMID 33766119, 2021). "IGF-1R, EGFR, and VEGF can bind to RTKs, which will activate RAS-RAF-MAPK and PI3K/AKT/mTOR signaling pathways, promoting tumor growth, progression, cell survival, motility, and invasion." (PMID 34638601, 2021). "MiRNA-99a was also found to directly target insulin-like growth factor 1 receptor (IGF-1R) and mTOR, suggesting that miR-99a is a promising tumor suppressor for HCC." (PMID 34582645, 2021). "We demonstrate that combining dabrafenib and trametinib with an IGF1R/IR inhibitor, BMS-754807, in vitro and in vivo, is efficacious and inhibits proliferation and tumor growth." (PMID 34831014, 2021). "To further investigate the biological function of IGF1R in PCAT6‐induced BM and tumor growth, we overexpressed IGF1R in PCAT6‐silenced PC‐3 and C4‐2B cells." (PMID 34185427, 2021). "By analyzing a CLIP‐Seq dataset reported in a previous study, we found that some mRNAs among the top 100 IGF2BP2‐binding mRNAs, such as C‐MYC, AKT3, IGF1R, and CCND2, were closely related to tumor progression." (PMID 34185427, 2021). "Enhanced translation of IGF2 and IGF1R occurs via the de novo expression of the oncofetal RNA-binding proteins IGF2BPs (IGF2BP1, IGF2BP2, IGF2BP3) in different tumor types." (PMID 34440844, 2021). "BANCR silencing reduced in vivo tumor growth, migration, and EMT via miR-338-3p sponging, which resulted in inhibition of the IGF1R/Raf/MEK/ERK pathway in ESCC cells." (PMID 33827418, 2021). "IGF-1R, together with mesenchymal-epithelial transition (MET), is frequently overexpressed by various tumor types, including CRC." (PMID 34638601, 2021). "Meanwhile, knocking down IGF-1R by shRNA or preventing IGF-1R phosphorylation by ceritinib enhanced the efficacy of sorafenib, reducing cell proliferation rate and tumor development." (PMID 33669204, 2021). "Insulin-like growth factor 1 receptor (IGF-1R), one of the main members of tyrosine protein kinase receptor family, plays an important role in maintaining the malignant phenotype and tumor anti-apoptosis." (PMID 34804946, 2021). "IGF2 is highly expressed in a variety of tumor tissues, and activates the IGF1 signal pathway and promotes cancer progression on binding with IGF1R." (PMID 34335947, 2021). "This can explain why, even though IGF1R targeting in preclinical models showed high activity in CRC and across tumor types, IGF1R inhibition failed in clinical trials." (PMID 34065119, 2021). "Meanwhile, YAP, IGF-1R, and mesenchymal markers (VIMENTIN and SNAIL1) were consistently observed at the tumor margin." (PMID 34359714, 2021). "Knocking-down IGF2 with siRNA, or blocking IGF1R with AEW541, resulted in superior anti-tumor activity of isiPI3K in vitro and ex vivo." (PMID 34067117, 2021). "IGF1R/IGF interaction activates Raf/MEK/ERK and P13K/AKT/mTOR signaling pathways, which are critical processes during tumor progression." (PMID 33827418, 2021). "LncRNA PVT1 was found to be upregulated in PTC—combined with IGF1R overexpression and miR-30a downregulation—and is related to TNM stage, lymph node metastasis, and tumor infiltration." (PMID 35186709, 2021).
tumor (continued). "In the absence of collagen and in the presence of IGFs, DDR1 enhances the IR-A and IGF-1R pathways, thereby increasing tumor cell migration and survival through the PI3K/AKT pathway and tumor growth through the Ras/Raf/MEK/ERK pathway." (PMID 33917302, 2021). "Unexpectedly, we found that, in addition to efficiently activate IGF1R, IGF1 also induced the phosphorylation of PDGFRα in mouse tumor OPCs." (PMID 33173731, 2020). "Activation of IGF1R promotes cellular motility through altered cell surface integrin expression by activation of downstream IRS2, FAK, RHOA, ROCK signaling led to tumor invasion and metastasis." (PMID 32570949, 2020). "IGF1R, a transmembrane receptor tyrosine kinase upregulated in NSCLC, is correlated with tumor progression and patient prognosis." (PMID 32971893, 2020). "It is worth mentioning that the IGF-1R, FAK and YAP/TAZ inhibitors used in the present study, enhanced the efficacy of diverse chemotherapeutics in different tumor contexts further corroborating their usefulness as antitumor agents." (PMID 32325700, 2020). "According to SHAP analysis data the most influential gene in the pathway is Insulin-like Growth Factor 1 Receptor (IG1FR), which has an important role in tumor growth and survival." (PMID 32299344, 2020). "Insulin-like growth factor I receptor-1 mediated IGF-1R activation induces proliferation, epithelial-mesenchymal transition (EMT), metastasis, drug resistance, and tumor recurrence." (PMID 32754598, 2020). "Marked overexpression of DUSP4, CD44, MUM1/IRF4, BCL-2, CD146/MUC18, IGF1R, and AKT3 was observed in the tumour cells in all mUM, compared to the background hepatocytes." (PMID 33008022, 2020). "The co-inhibition of IGF-1R and EGFR inhibits tumor-initiating potential and increases sensitivity to radiation therapy in pancreatic CSCs." (PMID 33511137, 2020). "In patient 9, SMO, NTRK3, IDH2, IGF1R, and CDK12 were also amplified in tumour #1 in addition to ERBB2 amplification." (PMID 31929516, 2020). "It was previously shown that insulin-like growth factor 1 receptor (IGF-1R) inhibition enhanced the effect of CDK4/6 inhibitors on suppression of ES cell proliferation and tumor formation." (PMID 32477459, 2020). "Combination treatment with an IGF-1R inhibitor and CDK4/6 inhibitor demonstrated synergistic activity by inhibiting tumor growth and survival of ES cells in vivo and in vitro through the suppression of PKC/AKT/mTOR and activation of RB." (PMID 32754598, 2020). "Results of the present study demonstrate that AE treatment suppresses expression of angiogenesis-related proteins namely, HIF-1α and IGF1R in HGSOC cells and, also in HGSOC derived xenograft tumor." (PMID 32194804, 2020). "A large number of oncogenes as target genes of miR-505 in tumor cells, including TGF-α, HMGB1, FZD4, IGF1R, WNT7B, MAP3K3, NRCAM, and RUNX2, have been recognized as direct target genes of miR-505." (PMID 33520999, 2020). "First, our results demonstrated that PSPC1 is the upstream modulator of IGF1R expression to activate downstream FAK/Src focal adhesion signaling and facilitate cell motility that is crucial for tumor progression." (PMID 32570949, 2020). "Among these genes, we found that IGF1R and CDK6 that are involved in regulation of cancer cell proliferation and tumor growth." (PMID 33219221, 2020). "Concurrent inhibition of IGF1R and CDK4/6 has shown a greater decrease in cell viability than achieved by a single drug in both NCI-H295R and MUC1 cells, as reported in different tumor cell lines." (PMID 32373071, 2020). "miR-7 also directly targets insulin-like growth factor 1 receptor (IGF1R), FAK, and PAK1, which can inhibit the proliferation, migration, invasion, and epithelial-mesenchymal transition (EMT) of tumor cells." (PMID 32090067, 2020).
tumor (continued). "Paraptosis was initially observed in 293T cells and mouse embryonic fibroblasts overexpressing insulin-like growth factor 1 receptor (IGF-1R) and was subsequently shown to be induced by different natural compounds in vitro and in vivo in tumor cells." (PMID 33585447, 2020). "IGF-1R and FGFR are continuously activated in sorafenib-resistant HCC, and these sorafenib-resistant tumor cells exhibit greater tumor-initiating capacity in vivo." (PMID 33511137, 2020). "A combination of OSI-906 and Palbociclib (a CDK4/6 inhibitor) markedly decreased tumor growth in a PDOX model by suppressing the CDK4/6 and IGF-1R pathways." (PMID 32754598, 2020). "IGF-1 signals intracellularly through the PI3 and MAPK pathways after binding to IGF-1R on the cell surface, and IGF-1 thereby increases the enzymatic activity of MMP-2 and MMP-9 and enhances the proliferation and migration of tumor cells." (PMID 32972437, 2020). "In tumor cells and endothelial cells, stimulation with ligands of cell surface GRP78, such as α2-macroglobulin, T-cadherin, Cripto, and insulin-like growth factor 1 receptor, induces activation of the PI3K-Akt signaling." (PMID 32547396, 2020). "MiR-99a down-regulated in ESCC significantly promoted tumor cell proliferation, migration, invasion, and slug-induced EMT through activating the IGF1R signaling pathway." (PMID 32662828, 2020). "Therefore, IGFBPs may be a possible tumor suppressor in tumors with active IGF1R signaling." (PMID 33260481, 2020). "Activation of the IL-6/STAT3 pathway induces the expression of IGF-1/IGF-1R, thereby initiating the IGF-1/IGF-1R autocrine and paracrine loop within tumor bulk to induce stemness-related gene expression." (PMID 33511137, 2020). "Before, interactions with IGF1R, EGFR and MET receptors had been shown for flRON and several studies had demonstrated MSP-mediated tumor proliferation and progression involving the PI3K/AKT signaling pathway." (PMID 32272784, 2020). "Predicted genes targeted by dysregulated oncomiRs or tumor suppressor miRNAs were mainly involved in cell cycle regulators such as CAPRIN1, CDC42, PTEN, IGF1R, BRCA1 and CD28, thereby controlling cancer dormancy." (PMID 33374139, 2020). "Targeting IGF-1R with figitumumab reduces side population cells and ALDH+ populations and also inhibits xenograft tumor growth." (PMID 33511137, 2020). "As a result, we found IR-A and IGFIR expression was positively correlated, but IR-A showed a significant higher expression than IGF1R in tumor tissues (p<0.05)." (PMID 33173015, 2020). "In this study, we find that β-elemene represses the proliferation of ESFT cells, enhances the anti-growth effects of IGF1R inhibitors on ESFT cells and decreases the phosphorylation of IR in tumor cells other than normal hepatocytes." (PMID 30422809, 2019). "In vivo, insulin receptor (IR)/ insulin-like growth factor 1 receptor (IGF1R) signaling positively regulates fibroblast proliferation and activation, reducing tumor growth." (PMID 31014370, 2019). "Our group reported that IGF-1R siRNA efficacy is influenced by secondary structure in Igf1r mRNA, leading to design of IGF-1R siRNAs that induced profound IGF1R silencing and enhanced tumor cell radiosensitivity." (PMID 31416218, 2019). "We elucidated an autocrine loop of IL-6/IGF-1R/STAT3 in EMT-mediated resistance and tumor growth in NSCLC." (PMID 31523190, 2019). "Our previous study demonstrated that HBV-derived niche IL-6 can upregulate OCT4 expression through insulin-like growth factor 1 receptor (IGF-1R) signaling and the OCT4 expression can result in early tumor recurrence." (PMID 31771617, 2019). "The proliferation of the patient tumor cells (225ZL) was inhibited by arsenic trioxide (ATO), which is an inhibitor of the SHH pathway, by linsitinib, which is an inhibitor of IGF1R and INSR, and by ceritinib." (PMID 31480400, 2019).
tumor (continued). "They exhibited potent antitumor activity against a panel of tumor cell lines, including HCT-116 and HepG2, with IC50 values < 10 μg/mL, in addition to inhibitory activity against tumor growth-related tyrosine kinases, including FGFR3, IGF1R, PDGFRb, and TRKB." (PMID 31174259, 2019). "Investigations in several different tumour types have revealed increased IGF activity in chemoresistant tumours and shown that IGF1R inhibition acts as a chemosensitizer." (PMID 31179642, 2019). "As inhibition of tumor growth by TAE226 appears to correlate with inhibition of FAK and Akt as a surrogate of IGF-1R signaling pathway, TAE226 represents a novel class of selective and small molecule kinase inhibitor with a potent in vivo activity." (PMID 31215459, 2019). "These cell lines stem from disparate tumor or tissue types, but they were all predicted to have very high recruitment of CRKL (more than one copy of CRKL bound to each molecule of IGF1R) coupled with moderately high recruitment of either SRC, SHC1, or RASA1." (PMID 30653502, 2019). "Tumor Microarrays were successfully stained for p-ER, EGFR, p-ERK1/2, p-mTOR, and IGF1R, and scored by a breast pathologist." (PMID 29486734, 2018). "Since MET and IGF1R expression limited the efficacy of GDC0032, we investigated the effect of these receptors on tumor cell viability in the presence of GDC0032 by conducting a head-to-head synergistic drug combination." (PMID 30237504, 2018). "In the study of cell lines, IGF-1R leads to EGFR-TKI resistance by regulating the metabolism, proliferation and apoptosis of tumor cells and continuously activating the PI3K-AKT signaling pathway." (PMID 29455664, 2018). "As key targets of miR-122-5p, IGF-1R and PKM2 have been reported to promote tumor growth and metastasis, indicating the functional similarity of UCA1." (PMID 29669595, 2018). "Positive membrane staining of IGF1R and positive nuclear staining of HMGA2 were observed in tumor tissues, with no or weak immunoreactivity of these proteins in adjacent non-tumor tissues." (PMID 29507664, 2018). "Recent evidence also illustrates the role of IGF1R in the maintenance of cancer stem cells, in epithelial‐to‐mesenchymal transition (EMT), and in the regulation of tumor microenvironment." (PMID 28766847, 2018). "We noted that the inhibition of IGF1R, MET, and AKT had a greater anti-tumor effect when combined with GDC0032 in both IGROV1Res and OAW42Res." (PMID 30237504, 2018). "Taken together, these data indicate that reduced epithelial IGF-1R function in MMTV-Wnt1 tumors results in an influx of immune cells that enhance tumor growth and contribute to an aggressive tumor microenvironment." (PMID 30458886, 2018). "Knockdown of IGF1R re-sensitized cells to GDC0032 in vitro, and the combination of AEW541, an IGF1R inhibitor, with GDC0032 exhibited potent anti-tumor activity in vitro and in vivo." (PMID 30237504, 2018). "Insulin like growth factors (IGFs) constitute an important class of mitogens that activate receptor tyrosine kinases by binding to their receptor IGF-1R, and initiate the downstream PI3K/AKT signaling pathway to induce tumor development." (PMID 29566713, 2018). "We focus on the involvement of IGF1R signaling in DCs and present our preliminary results which imply that the IGF axis contributes to an immunosuppressive tumor microenvironment (TME)." (PMID 29922232, 2018). "In vitro and in vivo studies have shown that endogenous and exogenous insulin can stimulate tumor promotion via INSR and IGF1R." (PMID 29486734, 2018). "These pathways involve ESR1, IGF1R, and pro-death UPR-mediated apoptosis and inflammation with subsequent recruitment of tumor-infiltrating lymphocytes." (PMID 29796176, 2018). "Consistent with our mouse tumor model with reduced IGF-1R signaling, low IGF-1R is inversely correlated with IL-6, CCL2, and MMP9 expression in human tumors." (PMID 30458886, 2018).